IL22 (interleukin 22)
Diseases named in the same sentence as IL22 in open-access papers (continued):
Sharing a sentence is not in itself a finding about the gene and the disease.
Sepsis (continued). "While these results highlight that CR could cause sepsis-associated lethality under SPF condition, it remains puzzling whether the lethality in SPF Il22-/- animals attributes to the spread of CR per se or the synergistic CR-gut microbiota interactions." (PMID 39630719, 2024). "While IL-22 plays a key role in immunoregulation and has been linked to the development of organ failure in mouse models of abdominal sepsis, DAG-deepVASE revealed the causal relationship from IL-22 to SIRS status in children with sepsis." (PMID 37395630, 2022). "Firstly, this is a pilot study to explore the potential roles of IL-22 in SALI, and the small sample size of patients with sepsis affected the assessment of IL-22 for discriminating SALI from sepsis, and this conclusion requires further investigation in a larger population." (PMID 33177520, 2020). "At last, the kinetics of IL-22 secretion and the factors regulating IL-22 production in patients with sepsis remain unknown and should be investigated in the future." (PMID 33177520, 2020). "Furthermore, the IL-22BP derived from Fcγ2a fusion protein can serve as an antagonist to the effects of IL-22 during acute sepsis, and suggests a potential therapeutic intervention for polymicrobial peritonitis." (PMID 26793707, 2015). "It is believed that IL-22 that is produced during sepsis may contribute to host defense and to stabilizing mucosal barrier functions under systemic infection conditions." (PMID 25614712, 2014). "This dual role of IL-22 implies that it participates in the pathophysiology of experimental sepsis." (PMID 25614712, 2014). "Also, IL-22 plays a pivotal role in chronic inflammatory diseases and polymicrobial sepsis." (PMID 36562037, 2022). "The cecal gene expression of IL-6, IL-1β, TNF-α, IL-17A, IL-22, and CRAMP (homologue of human cathelicidin LL-37) was significantly elevated in mice with gut-derived P. aeruginosa sepsis." (PMID 38790988, 2024). "Even though IL-22 plays as an anti-inflammatory cytokine in IBD and sepsis-induced liver injury, its role in the inflamed-brain is still not elucidated." (PMID 35054942, 2022). "In the ileal tissues of healthy mice, sepsis EVs (S-EVs) downregulated messages of the pro-inflammatory cytokines including TNF-α, IL-1β, IL-6, IL-17A, and IL-22." (PMID 33182773, 2020). "Model mice were treated with IL-33 or its receptor ST2 in order to determine the effects of IL-33 on IL-17A, IL-22, and PGE2 in septicemia." (PMID 33178181, 2020). "In the current study, a septicemic mouse model was established by infecting mice with S. epidermidis (ATCC 12228) in order to analyze the effects of IL-33 on the development of septicemia and the production of PGE2, IL-17A, and IL-22." (PMID 33178181, 2020). "Moreover, the Sézary cells of one patient who developed sepsis stained positive for CD8 and produced IL-22." (PMID 34948183, 2021). "Moreover, IL22 has been reported to relieve sepsis-induced liver injury via activating the JAK/STAT3 signaling pathway, suggesting that IL22-producing ILC3s exert regulatory functions on damaged tissues other than the intestine." (PMID 33513946, 2021). "Other biomarkers that can indicate the immune state in sepsis patients include apoptosis markers (Bim, Bid and Bac), caspases, leukocyte markers (HLA-DR, PD-1, FOXP3, CD127) and cytokines (IL-2, IL-6, IL-12, IL-17, IL-22, IL-33, TNF-α, IFN-γ, IL-10 and TGF-β)." (PMID 33336293, 2020). "Plasma levels of IL22 were unaltered, suggesting that the protective effect of mPGES-1 in MI/R does not rely on IL22, a cytokine that restrains sepsis-related systemic inflammation downstream of PGE237." (PMID 31015404, 2019). "In addition, measured levels of IL-22 at different days after admission in children with sepsis, or in children with non-septic liver injury or healthy children were unavailable due to the lack of blood samples in children in the present study." (PMID 33177520, 2020).
Chronic colitis (22 papers, 2016 to 2025). A chronic inflammatory disease of the large intestine (colon, cecum and rectum). "Taken together these data support a pathogenic role for IL22-induced colonic epithelial ER stress in chronic colitis." (PMID 31792136, 2020). "In conclusion, data presented in this study advance our understanding of IL22 biology in the colon and cast new light on pathogenic mechanisms of this important cytokine in chronic colitis." (PMID 31792136, 2020). "Similarly, intestinal organoids treated with low doses of pro-inflammatory IL-22 or the chronic colitis-associated cytokine TNF-α, displayed a small but significant increase in the percentage of Lgr5+ CBC cells." (PMID 32948837, 2020). "IL-22-producing CD4 T cells are found to be pathogenic in a model of chronic colitis." (PMID 28408906, 2017). "In mice, this pathway was crucial for optimal production of IL-22 and IL-17 by ILC3s, leading to resistance against acute infections caused by C. difficile or C. rodentium, acute colitis induced by DSS, and chronic colitis induced by T cell transfer." (PMID 38722686, 2024). "Our data also support the notion that IL-22-mediated induction of CXC-family chemokines is functionally important in the recruitment of CXCR2+ neutrophils to the colon in chronic colitis." (PMID 36192482, 2022). "Our previous investigation revealed that the therapeutic effects of SSW were mediated by depressing the levels of IFN-γ and IL-17A in acute UC mice models and upregulating the content of IL-22 in chronic colitis." (PMID 34956391, 2021). "Our data challenge perceptions of IL22 as a predominantly beneficial cytokine in IBD and provide novel insights into the molecular mechanisms of IL22-mediated pathogenicity in chronic colitis." (PMID 31792136, 2020). "Blocking IL-22 ameliorated colonic epithelial ER stress and attenuated the IL-22-dependent model of chronic colitis in mice." (PMID 33584726, 2020). "To investigate the functional role of IL22 in chronic colitis and how it regulates colonic epithelial cells, we employed a three-dimentional mini-gut epithelial organoid system, in vivo disease models and transcriptomic datasets in human IBD." (PMID 31792136, 2020). "In this study, we evaluated the functional role of IL22 in chronic colitis and probed mechanisms of IL22-mediated regulation of colonic epithelial cells." (PMID 31792136, 2020). "In a Th2-mediated chronic colitis model (TCRα KO mice) representing UC, IL-22 was shown to play a protective role by reinforcing intestinal mucus barrier function." (PMID 29075900, 2018). "Although the involvement of IL-22 in mucosal healing has been reported reproducibly by many groups, the different roles of IL-22 have been demonstrated in chronic colitis models." (PMID 29075900, 2018). "Likewise, Gunasekera and colleagues have demonstrated the mechanistic relationship between IL-10 and IL-22, suggesting important insights into the pathogenesis of chronic colitis in IL-10−/− mice." (PMID 40830617, 2025). "Interestingly, a recent study demonstrates that IL-22 promotes chronic colitis through facilitating the endoplasmic reticulum stress response in colonic epithelial cells." (PMID 36361787, 2022). "It needs to be actively pursued whether IL-22BP has therapeutic value for human IBD, in lieu of IL-22-induced colonic epithelial ER stress and completely attenuated chronic colitis in IL-22-/- mice or by anti-IL-22 neutralization." (PMID 34992594, 2021). "Importantly, a recent study reveals that IL-22 plays a detrimental role in chronic colitis through enhancing the endoplasmic reticulum stress response in colonic epithelial cells, adding a new mechanism for the context-dependent pathogenic actions of IL-22 in epithelial tissues." (PMID 36361787, 2022). "Next, we asked whether the IL22/ER stress axis was functionally important in chronic colitis." (PMID 31792136, 2020).
Chronic colitis (continued). "Blockade, genetic deletion of IL-22, or blockade of CXCR2, the common ligand for the CXC family of neutrophil-active chemokines, significantly attenuated disease in the TRUC model of chronic colitis." (PMID 36192482, 2022). "In summary, our data demonstrated that L-fucose played a therapeutic role in ameliorating DSS-induced chronic colitis in mice by accelerating ISC proliferation, and it works through the AHR/IL-22 pathway of LPMCs." (PMID 36432480, 2022). "Alternatively, in a chronic colitis model that is induced by the adoptive transfer of memory CD4+ T cells, a proinflammatory role of memory T cell-derived IL-22 was proposed." (PMID 29075900, 2018). "In a chronic colitis model, TNF-α stimulated the IL-22BP expression in CD4+ T cells, leading to the suppression of IL-22-dependent mucosal healing." (PMID 29075900, 2018). "Despite validation of a protective role of IL-22-producing CD4 T cells in acute colitis, paradoxically it can also contribute to intestinal pathology during chronic colitis." (PMID 28408906, 2017). "Il‐10−/−Il‐22−/− nor Il‐22−/− mice develop chronic colitis, indicating that IL‐22 is involved in chronic colitis development." (PMID 38363052, 2024). "Given the important role of IL-22 in the maintenance of ISC homeostasis, we found that the exogenous administration of L-fucose significantly increased intestinal IL-22 secretion and IL-22R expression in DSS-induced chronic colitis." (PMID 36432480, 2022). "For the first time we show that IL22 performs a non-redundant, pathogenic role in the TRUC model of chronic colitis." (PMID 31792136, 2020). "RORγt+ ILCs and transformed ILC1s may eventually worsen intestinal inflammation via IL-22 and IFN-γ, respectively, in chronic colitis when IL-17A is absent." (PMID 31941937, 2020).
graft versus host disease (22 papers, 2014 to 2025). An immune system disorder that occurs after allogeneic hematopoietic stem cell transplant and is a reaction of donor immune cells against host tissues. "The role of IL-22 in adult patients undergoing allogeneic stem cell transplantation (SCT) is of major interest since animal studies showed a protective and regenerative effect of IL-22 in graft versus host disease (GvHD)." (PMID 35572572, 2022). "Another beneficial effector function of ILC3-derived IL-22 was observed in a mouse model of graft-versus-host disease (GVHD) and tissue damage, where IL-22 acts on intestinal stem cells to preserve the epithelial barrier integrity [42••, 43]." (PMID 27645534, 2016). "Likewise, IL-22 administration increased the recovery of Lgr5+ ISCs and epithelial regeneration in a graft-versus-host disease mice model." (PMID 38262747, 2024). "Recombinant human IL-22 is currently in Phase II clinical trials for the treatment of COVID-19 pneumonia, acute pancreatitis, chronic acute liver failure, alcoholic hepatitis, and graft-versus-host disease (GVHD) (NCT02406651)." (PMID 39596179, 2024). "Moreover, ILC3-derived IL-22 protects against tissue damage occurring in intestinal epithelial stem cells due to graft versus host disease (GvHD), which occurs after hematopoietic stem cell transplantation." (PMID 29232860, 2017). "ISCs have been found to express IL-22 receptor (IL-22R), through which IL-22 protects ISCs against inflammatory tissue damage mediated by graft versus host disease (GVHD)." (PMID 41467015, 2025). "Lastly, what is also not completely understood is the connection between the effects of IL-22, the microbiota and graft versus host disease (GvHD)." (PMID 33003458, 2020). "IL-22 also acts on intestinal epithelial stem cells, and radio-resistant IL-22-producing ILC3s from the recipient are key to limit the severity of intestinal damage during graft versus host disease (GVHD)." (PMID 24982658, 2014). "Other studies have enhanced wild-type L. lactis to secrete IL-27 to treat immune colitis, and genetically modified Lactobacillus reuteri to secrete IL-22 for conditions such as IBD and Graft versus Host Disease (GvHD)." (PMID 39233526, 2024). "In patients with AML treated by allogeneic HSCT, IL‐22 secreted by ILC3s might forestall graft versus host disease (GVHD), and thus IL‐22 could be a feasible treatment option." (PMID 36246629, 2022). "In addition, it was reported that IL-22 is produced by recipient ILC3s, which can persist after bone marrow transplant (BMT) and protect ICSs from immune-mediated tissue damage by graft versus host disease (GVHD)." (PMID 33396437, 2020). "In graft-versus-host disease (GVHD) patients, oral administration of Bacteroides fragilis increased the levels of short chain fatty acids (SCFAs) and IL-22, as well as the number of regulatory T cells, which may account for the improved tight junction integrity and reduced inflammation." (PMID 35795671, 2022).
uveitis (22 papers, 2011 to 2025). An inflammatory process affecting a part of or the entire uvea. "Pairwise comparisons between IOL, ARN, and BE revealed that levels of IL-10 in IOL, RANTES (regulated on activation, normal T cell expressed and secreted) in ARN, and IL-22 in BE were significantly higher than those in the other 2 types of uveitis." (PMID 32066796, 2020). "Our data suggest that the aetiology-specific inflammatory mediators that are elevated in the disease entities associated with uveitis included in this study are IL-10 in IOL, RANTES and IFN-α2 in ARN, and IL-6, IL-17A, IL-22, and G-CSF in BE." (PMID 32066796, 2020). "Tregs are thought to regulate the expression of IL-22, a Th17 cytokine which facilitates inflammatory cell infiltration in uveitis." (PMID 29774027, 2018). "We have previously reported that Th2 and Th17 cell-related cytokines; specifically IL-4, IL-10, IL-17A, IL-22, IL-31and TNFα, are exclusively elevated in the vitreous fluid of PDR compared with that of ERM, MH, or uveitis associated with sarcoidosis." (PMID 28558009, 2017). "In this study, we aimed to determine the specific role of IL-22 and its receptor in the pathogenesis of uveitis." (PMID 27166675, 2016). "Percent detectable of IL-4 and IL-22 were significantly higher in PDR group than in uveitis group, although those of IFN-γ and sCD40L were significantly higher in uveitis group compared with PDR group." (PMID 26352837, 2015). "In a preclinical model of uveitis IL-22 is protective when administered prior to the onset of inflammation." (PMID 24676270, 2014). "These experiments also showed that the frequency of IL-22 -positive CD4+ T cells was significantly higher in BD patients with active uveitis." (PMID 23527071, 2013). "An increased frequency of IL-22-producing CD4+T cells was also found in BD patients with active uveitis." (PMID 23527071, 2013). "The increased IL-22 expression observed in our study seemed to be unique to active BD in view of its normal expression in AAU patients although its expression in other uveitis entities still needs to be investigated." (PMID 23527071, 2013). "The results showed a significantly elevated IL-22 production by activated CD4+ T cells in BD patients with active uveitis." (PMID 23527071, 2013). "The group of Nussenblatt from the NIH have clearly shown an upregulated expression of IL-22 in clinical uveitis." (PMID 23527071, 2013). "IL-22 is expressed in uveitis, in which IL-22 decreases total tissue resistance and induces apoptosis in retinal pigment epithelial cells." (PMID 22312190, 2012). "IL-17A protein and IL-22 mRNA were found to be highly expressed by peripheral blood mononuclear cells (PBMCs) from uveitis patients." (PMID 21479174, 2011). "A recent study showed an increased expression of IL-22 by PBMCs from uveitis patients, suggesting its possible involvement in this disease." (PMID 21479174, 2011). "Serum concentration of IL-22 was significantly increased in uveitis patients." (PMID 27166675, 2016). "IL-22 producing CD4+ cells have been reported to play a role in BD patients with active uveitis." (PMID 25061613, 2014). "The results showed that the frequency of IL-22/IL-17 double positive CD4+T cells from BD patients with active uveitis (0.86%±0.27%) was significantly higher than in BD patients without active uveitis (0.40%±0.13%, p<0.001) or normal controls (0.43%±0.15%, p = 0.001)." (PMID 23527071, 2013). "There is also some controversy concerning the role of IL-22 in uveitis." (PMID 23527071, 2013). "Although IL-22 can have both pro-inflammatory and anti-inflammatory roles, its pro-inflammatory roles have been studied most extensively, and several studies have shown correlations between IL-22 production and inflammatory skin conditions, uveitis, Alzheimer’s disease, and liver injury." (PMID 35054942, 2022).